IGKV2-28 (immunoglobulin kappa variable 2-28)
Description:
V region of the variable domain of immunoglobulin light chains that participates in the antigen recognition. Immunoglobulins, also known as antibodies, are membrane-bound or secreted glycoproteins produced by B lymphocytes. In the recognition phase of humoral immunity, the membrane-bound immunoglobulins serve as receptors which, upon binding of a specific antigen, trigger the clonal expansion and differentiation of B lymphocytes into immunoglobulins-secreting plasma cells. Secreted immunoglobulins mediate the effector phase of humoral immunity, which results in the elimination of bound antigens. The antigen binding site is formed by the variable domain of one heavy chain, together with that of its associated light chain. Thus, each immunoglobulin has two antigen binding sites with remarkable affinity for a particular antigen. The variable domains are assembled by a process called V-(D)-J rearrangement and can then be subjected to somatic hypermutations which, after exposure to antigen and selection, allow affinity maturation for a particular antigen.
Synonyms: A19; IGKV228
Gene: Immunoglobulin variable (V) gene on chromosome 2 (89,221,698 to 89,222,461, reverse strand). Ensembl gene ENSG00000244116.
Subcellular location: Secreted; Cell membrane
Pathways (Reactome):
Immune System: Antigen activates B Cell Receptor (BCR) leading to generation of second messengers; CD22 mediated BCR regulation; Classical antibody-mediated complement activation; FCERI mediated Ca+2 mobilization; FCERI mediated MAPK activation; FCERI mediated NF-kB activation; FCGR activation; Fc epsilon receptor (FCERI) signaling; Immunoregulatory interactions between a Lymphoid and a non-Lymphoid cell; Initial triggering of complement; Regulation of Complement cascade; Regulation of actin dynamics for phagocytic cup formation; Role of LAT2/NTAL/LAB on calcium mobilization; Role of phospholipids in phagocytosis
Disease: FCGR3A-mediated IL10 synthesis; FCGR3A-mediated phagocytosis; Potential therapeutics for SARS
Hemostasis: Cell surface interactions at the vascular wall
Vesicle-mediated transport: Scavenging of heme from plasma
Gene Ontology:
Biological process: immune response
Cellular component: extracellular region; immunoglobulin complex; plasma membrane
Homologues: Orthologues: mouse Igkv2-109 (78% identical). Paralogues in human: IGKV2D-28 (100% identical), IGKV2D-40 (88% identical), IGKV2D-29 (85% identical), IGKV2-24 (82% identical), IGKV2-30 (82% identical), IGKV2D-30 (81% identical), IGKV2D-24 (80% identical), IGKV2D-26 (79% identical), IGKV2-40 (75% identical), IGKV4-1 (62% identical), IGKV3-20 (61% identical), IGKV3-11 (60% identical), and 81 more.